LAG3 (lymphocyte activating 3)
Diseases named in the same sentence as LAG3 in open-access papers (continued):
Sharing a sentence is not in itself a finding about the gene and the disease.
cancer (continued). "We found that CD161 was positively correlated with marker genes of exhausted T cells, immune activating genes, and immunosuppressive genes in pan-cancer such as TIGIT, PDCD1, LAG3, CTLA4, STING1, CD96, and IDO1." (PMID 34305920, 2021). "Methylation of CpGs annotated to the promoters of LAG3, CTLA4, CD86, CD80, and HAVCR2 also decreases with age pan-cancer." (PMID 34433020, 2021). "A number of immune checkpoint proteins were shown to be dysregulated in cancers and infectious diseases, including PD-1/PD-L1, CTLA-4, lymphocyte activation 3 (LAG-3), TIM-3, VISTA, and Indoleamine-2,3 dioxygenase 1 (IDO1)." (PMID 34917131, 2021). "FGL-1 is upregulated in several human cancers, and genetic ablation or blockade of the FGL-1/LAG-3 interaction by monoclonal antibodies (mAbs) would enhance T-cell responses and antitumor immunity." (PMID 34917131, 2021). "We found that the expression level of GRWD1 was positively correlated with the expression levels of immune checkpoint-related genes (CD274, CTLA4, HAVCR2, LAG3, PDCD1, PDCD1LG2, SIGLEC15, and TIGIT) in most types of cancer, especially in STAD." (PMID 34616846, 2021). "PRDM1 expression positively correlates with the expression of LAG3, CTLA4, PDCD1 (PD-1), CD274 (PD-L1), PDCD1LG2 (PD-L2), TIGIT in the majority of 33 cancer types." (PMID 33384601, 2020). "In preclinical studies of murine models of cancer, LAG-3 and PD1 have been shown to be co-expressed on both CD4+ and CD8+ TILs, and co-blockade of the Lag-3 and PD1 pathways has been shown to synergize to improve antitumor CD8+ T cell responses." (PMID 32944390, 2020). "The results showed that CTLA-4, IDO1, LAG-3, TIGIT and PD1 were specifically increased most in TBNC among different types of cancer." (PMID 32602545, 2020). "Generally, PRDM1 expression positively correlates with the expression of LAG3, CTLA4, PDCD1 (PD-1), CD274 (PD-L1), PDCD1LG2 (PD-L2), TIGIT in the majority of 33 cancer types." (PMID 33384601, 2020). "Lag‐3 is a transmembrane protein primary found on activated T cells and represent a function exhaustion of CD8+ T cells similar to PD‐1 in response to cancers." (PMID 32810392, 2020). "Among these next-generation ICPs, lymphocyte activating gene-3 (LAG-3, CD233) has emerged as an eminent target in the development of cancer treatment and holds substantial prognostic value." (PMID 33374804, 2020). "Combining anti-PD-L1/anti-LAG-3 mAbs with AT further enhances the therapeutic effect of ICB and largely eradicates all cancer cells." (PMID 32165639, 2020). "A number of inhibitory immunoreceptors have been identified and studied in cancer in past decades, including but not limited to PD-1, CTLA-4, LAG3, TIM3, TIGIT and BTLA." (PMID 32467592, 2020). "A soluble recombinant LAG-3-Ig fusion protein, Eftilagimod alpha (IMP321), has been used as an immunological adjuvant for vaccination against various infections and cancer." (PMID 32117298, 2020). "We selected the most common ICs, some of which are being targeted in ongoing clinical trials or are approved for cancer immunotherapy, including TIM-3, LAG-3, TIGIT, VISTA, CTLA-4 and PD-1." (PMID 32393998, 2020). "More importantly, the expressions of several inhibitory receptors on the intratumoral CD8+ T cells, including PD-1, CTLA-4, LAG3 and TIM3 were upregulated, resulting in exhausted phenotypes that are frequently observed in cancer patients." (PMID 32331230, 2020). "We measured expression of the receptors PD-1, CEACAM-1, LAG-3, CD158b, NKG2A and TIM-3 on activated human peripheral blood-derived NK cells prior to and after exposure to cancer targets." (PMID 32858904, 2020). "The fact that FGL-1 levels in the blood of cancer patients correlates with poor prognosis and resistance to anti-PD-1/B7-H1 therapy suggests FGL-1 as a major contributor to LAG-3 immunoregulation." (PMID 33027962, 2020).
cancer (continued). "In conclusion, the present study was intended to depict the entity-wise expression of LAG3 in a large cohort of SGC, a group of carcinomas bearing only sparse therapeutic targets." (PMID 32232506, 2020). "In our comparison of four cancers, CTLA-4-TIGIT-PD-1-TIM-3-BTLA- LAG-3 were among those most increased in expression and having the greatest association with OS." (PMID 30922393, 2019). "Two additional immune checkpoint molecules investigated in the context of cancer immunotherapy include TIM-3 (T cell immunoglobulin and mucin domain-containing protein-3) and LAG-3 (lymphocyte activation gene-3, CD223)." (PMID 31007846, 2019). "At present, humanized anti-TIM3 (TSR-022), anti-LAG3 (MK-4280), and anti-TIGIT (BMS-986207) antibodies against various cancers are under clinical trials." (PMID 31379886, 2019). "Regarding receptors, there exhibited a strong correlation with PD-1 and receptors including TIGIT, CTLA-4, LAG3, BTLA, ICOS, TNFRSF9, CD27 in most types of cancer." (PMID 30607140, 2018). "These immune-related genes include those that are established or promising targets for cancer immunotherapy such as CTLA4, PD1, PD-L1, PD-L2, IDO1, LAG3, and TIGIT." (PMID 30089500, 2018). "Of note, LAG-3 signal can elevate sensitivity to Treg cells, which can mediate chronic exhaustion and inhibition of CD4+ T cells during cancer recurrence." (PMID 30603054, 2018). "In chronic viral infections and cancer, the co‐inhibitory receptors PD‐1, TIM‐3, and LAG‐3 are induced upon persistent antigen stimulation." (PMID 29349889, 2018). "Cancer cells bind to co-inhibitory molecules on T cell surface such as CTLA-4, PD-1, TIM-3, and LAG-3 which in turn secrete immune-suppressive mediators such as IDO (indoleamine 2,3-dioxygenase) to create an immune subversive environment in the TME." (PMID 30081950, 2018). "IL-27 induces inhibitory molecules including PD-1, Tim-3, LAG-3, TIGIT, and IL-10, which overlap with the mediators of T cell exhaustion, in chronic viral infections and cancer." (PMID 28545567, 2017). "In vitro LAG-3 blockade improves T cell functions, and the combined blockade of PD-1 and LAG-3 synergistically rescues T cells from exhaustion in many cancers and chronic infection models." (PMID 29023417, 2017). "LAG3-specific monoclonal antibody and LAG-Ig (IMP321) are in early phase clinical trials for cancer, these trials are still recruiting patients and thus it will be some time before trial data are available." (PMID 29225597, 2017). "Another important immune checkpoint is lymphocyte-activation gene 3 (LAG-3), highly expressed on activated T cells in many cancer types, that can be used as an immunotherapy target." (PMID 28572863, 2017). "Among them, LAG-3, Tim-3, and TIGIT are emerging immune checkpoints under preclinical and clinical development for cancer therapy." (PMID 28545567, 2017). "Similar to PD-1, TIM-3, and LAG-3, TIGIT is upregulated on exhausted T cells in both chronic viral infections and cancer." (PMID 26347741, 2015). "Additional non-CD28/B7 family receptors such as lymphocyte-activation gene-3 (LAG-3) and T cell immunoglobulin domain and mucin domain 3 (TIM-3) have been identified as potential targets in cancer." (PMID 24353898, 2013). "Functionality in response to polyclonal stimuli was not affected by cancer or therapy, although induction of LAG-3 and CTLA-4 was impaired in both Vδ1 and Vδ2 cells." (PMID 41310392, 2026). "This review provides a comprehensive overview of the regulation and therapeutic targeting of immune checkpoint proteins in cancer, covering both classical checkpoints, including PD-1, PD-L1, and CTLA-4, and emerging targets such as LAG-3, TIM-3, TIGIT, BTLA, SIRP-α, CD200, ILT4, and CD24." (PMID 42279386, 2026). "This review is limited in scope to ICIs (anti-CTLA-4, anti-PD-1, anti-PD-L1, anti-LAG-3) and does not detail other immunotherapeutic modalities (oncolytic viruses, cytokine therapies, adoptive cell transfer, cancer vaccines)." (PMID 42292486, 2026).
cancer (continued). "Novel therapeutic immune checkpoint inhibitors (ICIs) can block the negative effects of CTLA-4 and LAG3, allowing T cells to effectively target cancer cells." (PMID 41155207, 2025). "In addition, AURKA expression was significantly and positively correlated with immune checkpoint targets such as CD274, LAG3, and CTLA4 in most cancer types." (PMID 40718709, 2025). "In cancer immunotherapy, aptamers targeting immunological checkpoint molecules, including CTLA-4, TIM-3, and LAG-3, might replace monoclonal antibodies." (PMID 40870970, 2025). "Peptide LAG-3 inhibitors—both selective inhibitors of the LAG-3/FGL1 pathway, such as LFP-6 and LFP-D1, and cyclic LAG-3/MHC-II inhibitors, such as peptide 12—represent two complementary approaches to modulate LAG-3 function in cancer immunotherapy." (PMID 40574024, 2025). "Furthermore, in pan-cancer, TRPM6 was negatively correlated with CD274, LAG3, PDCD1, and SIGLEC15, and showed significant differences (P < 0.01)." (PMID 41562086, 2025). "The bispecific PD-1×LAG-3 molecule Tebotelimab showed safety and effectiveness in advanced cancer, generating responses in various solid tumors and LAG-3+ non-Hodgkin lymphomas, even with margetuximab." (PMID 40739089, 2025). "An Fc-attenuated LAG-3-TCR bispecific antibody has been engineered to suppress T cell activity independently of MHC-II, demonstrating therapeutic potential in autoimmune models and offering a new avenue for sustaining T-cell function in cancer immunotherapy." (PMID 41268548, 2025). "As cancer cells can upregulate alternative checkpoints, such as TIM-3 or LAG-3, aptamers targeting a single checkpoint (e.g., PD-L1/PD-1) may not be sufficient to overcome immune evasion mechanisms." (PMID 40870970, 2025). "CRISPR‐Cas9 significantly enhances CAR‐T outcomes by enabling precise CAR gene integration, mitigating T‐cell exhaustion through knockout of inhibitory genes (e.g., PD‐1, CTLA‐4, and LAG‐3), and improving CAR‐T survival and anti‐cancer effects by interfering with programmed cell death." (PMID 40685330, 2025). "LAG-3 is a key immune co-inhibitory receptor alongside PD-1 and TIGIT, reported in various cancers." (PMID 41300994, 2025). "Like PD-1, LAG-3 is an “exhaustion” marker of CD8 + T cells, indicating dysfunctional T cells from chronic stimulation, as seen in animal models of chronic infection and cancer." (PMID 40234667, 2025). "However, each gene in different cancers positively correlated (p < 0.05) with either its mRNA expression or CNVs, e.g., TIGIT in ACC, LAG3 in UVM, HAVCR2 in LUSC, LAYN in OV and PDCD1 in BLCA." (PMID 40076932, 2025). "Based on the upregulation of other immune checkpoints after PD-1/PD-L1 blockade treatment, we focus on the combination with other ICBs, including CTLA-4, TIM-3, LAG-3, TIGIT, VISTA, and some emerging immune checkpoints, so as to provide evidence for improving the benefit of ICBs in cancers." (PMID 40861801, 2025). "In recent years, with the discovery of the considerable therapeutic potential of cancer immunotherapy, researchers have developed new immune checkpoint targets, such as TIM3, lymphocyte activation gene 3 (LAG3), and tyrosine-based inhibition motif domain (TIGIT)." (PMID 40362568, 2025). "Non-redundant checkpoints increased in PD-1-resistant cancers include LAG-3, TIGIT, TIM-3, and VISTA." (PMID 41584608, 2025). "We previously demonstrated in an ex vivo A549 cancer cell-T cell interaction assay that peripheral blood T cells from NSCLC cancer patients need to be TCR stimulated to co-upregulate PD-1 and LAG-3, and to induce the transcriptional transactivation of E3 ubiquitin ligases." (PMID 39030301, 2024). "And one of the main mechanisms of cancer cell immune escape is to disrupt this immune synapse by expressing inhibitory ligands for T-cell activation, e.g., PD-1, CTLA-4; lymphocyte activation 3, LAG3; hepatitis A virus cell receptor 2, TIM3." (PMID 39146202, 2024).
cancer (continued). "Programmed cell death-1 (PD-1)/programmed cell death ligand-1 (PD-L1) pathway, cytotoxic T-lymphocyte antigen-4 (CTLA-4) pathway, and the recently discovered lymphocyte-activation gene 3 (LAG-3) pathway, play a critical role in boosting the body’s natural immune response against cancer cells." (PMID 38482205, 2024). "A next-generation checkpoint inhibitor antibody against lymphocyte activation gene-3 (LAG-3) was recently approved for a non-BC cancer indication." (PMID 38803496, 2024). "Therefore, further Pearson analysis was conducted to investigate the correlation between GPR65 and common cancer immune checkpoint inhibitors, such as CD200R1, CD47, HAVCR2, TIGIT, CTLA4, LAG3, and PD1." (PMID 38218960, 2024). "LAG3 is expressed in CD4 and CD8+ T cells, as well as T regs, and is required for optimal T cell regulation and homeostasis, and FGL1 was found to be highly expressed in human cancer cells." (PMID 39120585, 2024). "Cancer cells exerts immune evasion through several mechanisms, including the overexpression of cytotoxic T-lymphocyte antigen 4 (CTLA-4), Programmed death 1 (PD-1), or Lymphocyte-activation gene 3 (LAG-3)." (PMID 38322766, 2024). "Lymphocyte activation gene-3 (LAG-3) is an immune checkpoint receptor that delivers an inhibitory signal to activated T cells upon major histocompatibility complex (MHC) class II binding, and which is upregulated on infiltrating T cells in many cancer types." (PMID 39422598, 2024). "Nevertheless, based on the author’s recent publications, numerous clinical studies have focused on examining the combined effects of anti-PD-L1 with other treatments rather than concurrently treating different types of cancer with anti-LAG-3." (PMID 38390331, 2024). "Therefore, it would be more beneficial combining anti-PD1/L1 with another anti-cancer agent, such as chemotherapy for SCLC and TNBC, with TKI for RCC and HCC, and with anti-LAG3 or a BRAF/MEK inhibitor for melanoma." (PMID 38539487, 2024). "Specifically, ADAM10 regulates constitutive LAG3 cleavage, while ADAM17 regulates LAG3 cleavage induced by T cell receptor signaling, where ADAM17 showed immune and SARS-CoV-2 entry for the expression in patients with cancer." (PMID 39211038, 2024). "On the contrary, the transmembrane proteins that we will focus on, namely PD-1, CTLA-4, LAG-3, TIM-3, and TIGIT, are involved in the downregulation of a T-cellular immune response, including an anti-cancer immune response, preventing the cytotoxic T cells from killing cancer cells." (PMID 38893211, 2024). "LAG-3 and CTLA-4 both inhibit T cell activation and immune response against cancer." (PMID 39534873, 2024). "Some common and classical immune checkpoint genes such as LAG3, CD27, and TIGIT were most and significantly expressed in pattern B. The antitumor immune cycle works by activating and enhancing the immune system's ability to recognize and destroy cancer cells." (PMID 38322112, 2024). "Analysis of co-expression of two and more exhaustion markers shows that combination of BTLA and CD160 with or without LAG-3, conversely to other markers, show the maximum of downregulation in cancer samples." (PMID 39234236, 2024). "LAG-3 is currently being developed as a novel therapeutic target; however, it is not clear which ligands should be targeted for cancer therapy." (PMID 37179337, 2023). "With the role of this ICI in T cell exhaustion in cancer, it will be important to consider this as a mechanism in cardiovascular events in those without LAG-3, like the PD1(-/-) and CTLA-4-negative mice." (PMID 38136253, 2023). "Here, we analyzed the association of FAM110A with more than 40 immune checkpoint genes in pan-cancer based on the TCGA database and verified the correlation of FAM110A between several immune checkpoint genes, including PD-1, PD-L1, LAG-3, and CTLA-4 in the TIMER 2.0 database." (PMID 36923407, 2023).
cancer (continued). "LAG-3, an immunosuppressive checkpoint molecule, expressed in lymphocytes and its ligand GAL-3, has been identified on EC cells, particularly in nonmethylated dMMR cancers, supportting a role for immunotherapies targeting LAG-3 and/or GAL-3 in a subset of EC." (PMID 37368179, 2023). "However, there are indications that TIM3, LAG3 and VISTA expressions in cancer cells lead to an immunosuppressive TME, is of prognostic relevance, and thus a potential target for future ICIs." (PMID 36768480, 2023). "Thus, the aim of this study is to understand the landscape of IC in resected PDAC by investigating the presence of TIM3, IDO, B7H4, LAG3, VISTA, and PD-L1 in cancer cells and to determine their prognostic relevance in terms of overall survival (OS)." (PMID 36768480, 2023). "In fact, high LAG3 and TIGIT expression in infiltrated tumors could be indicative of a specific inflammatory milieu triggering LAG3 upon CD8+ T cell infiltration and sensitizing these cells to exhaustion signals from mesenchymal cancer cells." (PMID 38086828, 2023). "Besides CTLA-4, now several immune checkpoint receptors (ICRs), such as PD‐1, LAG3, TIM-3, B7‐H3, and diacylglycerol kinase α, have been also identified to treat cancer patients effectively." (PMID 36109471, 2023). "Taken together, these findings indicate that LAG-3 is an actionable target, with demonstrated efficacy in both resectable and non-resectable cancers; the clinical utility of LAG-3 inhibition in LMS is yet to be determined." (PMID 37046760, 2023). "Furthermore, positive correlations of PRC1 and some immune checkpoint genes (CD274, CTLA4, HAVCR2, LAG3, PDCD1, PDCD1LG2, TIGIT, and CD86) were observed in several cancers, especially BLCA, BRCA, KIRC, LUAD, LIHC, PRAD and THCA." (PMID 37563591, 2023). "Thus, six major ICs for cancer immunotherapy were analyzed in this work, namely CTLA4, PDCD1, CD274, ICOS, LAG3, and CD40." (PMID 37215135, 2023). "The same phenotype has been observed in cancer: Nrp-1 expression on CD8+ T cells was accompanied by elevated expression of CD44, CD69 and CD25, but also by several co-inhibitory molecules such as PD-1, CTLA-4, Lag-3 and Tim-3." (PMID 38019895, 2023). "CTLA4, LAG3, and PDCD1 are important targets for cancer ICI therapy." (PMID 38333724, 2023). "Researchers have found a number of immune checkpoint signals in cancers that could confer strong immunosuppression on cancer cells by combining ligands with inhibitory immunoreceptors, such as PD-1, TIGIT, CTLA-4, BTLA, LAG3, and TIM3." (PMID 36895440, 2023). "In addition, we also revealed that the Writer-Score was negatively related to the expression of PD-1, PD-L1, LAG-3 and CTLA-4 in majority of cancers." (PMID 37638051, 2023). "LAG-3 is not explicitly produced by cancer cells, whereas it is frequently observed in the pleural edema of mesothelioma individuals and tumor-invading lymphocytes." (PMID 37469419, 2023). "LAG‐3 inhibitors interact with LAG‐3 ligands on the surface of T‐cells to block T‐regulatory (Treg) cell activity, suppress cytokine secretion and restore dysfunctional effector T‐cells which subsequently attack and destroy cancer cells." (PMID 38047262, 2023). "In contrast, markers associated with suppressive populations of myeloid cells (CD163, B7-H3, VISTA) and T cells (CD4, LAG3, Tim-3) were expressed at a higher level in CD45+ segments in the ‘surrounding stromal leukocyte’ regions (cf. ‘immune-rich cancer cell islet’ regions)." (PMID 37046826, 2023). "Interestingly, the findings suggested a correlation between HIF1AN in breast malignancy and PDCD1, LAG3, CTLA4, and GZMB of T cell exhaustion as well as chemokine ligand CCL2 of TAMs." (PMID 36816977, 2023). "Moreover, we found that KIF18A had a positive correlation with immune checkpoints, such as PD-1, PD-L1, CTLA4, TIGIT, LAG3, HAVCR2, and PDCD1LG2 in a great many cancers." (PMID 36830695, 2023).